CD44 (CD44 molecule (IN blood group))
Diseases named in the same sentence as CD44 in open-access papers (continued):
Sharing a sentence is not in itself a finding about the gene and the disease.
tumor (continued). "The high expression of CD44 and high production of HA in tumor environments make them both prime targets for therapeutic intervention." (PMID 25954275, 2015). "In future studies, an intravenous dose of nCaPCMHACDDP at the maximum tolerable dose with optimized cell uptake and tumor infiltration should be examined in vivo to evaluate the targeting of therapy resistant CD44+ cells by chemically modified HA." (PMID 26448751, 2015). "We performed regression analysis to determine the impact of ALDH/CD44 marker combination on tumor growth rate." (PMID 26449187, 2015). "We observed tumor development in multiple tissues and organs following intra-cardiac injection of CD44-expressing MDA-MB-231 cells." (PMID 25888636, 2015). "Consistently, after inhibiting miR-101, SH-SY5Y control cells showed down-regulation of the tumor suppressor EDN1 and CD44 genes, and increased expression of the tumor progression ENPP2 gene with respect to LMNA-KD cells transfected with the miR-101 mimic." (PMID 26439802, 2015). "CD44 is known to contribute to tumor malignancy by modulating the adhesion of tumor cells to the extracellular matrix." (PMID 26189059, 2015). "Pro-inflammatory cytokines stimulate CD44 expression and strengthen CD44–HA binding in endothelial cells, which can capture haematopoietic cells and tumour cells." (PMID 26287771, 2015). "Self-assembling HA-coated nanoparticles were prepared to selectively target tumor cells with activated CD44 in vivo." (PMID 25909172, 2015). "Although the molecular mechanisms of the intracellular signaling in the tumor microenvironment that lead to CD44 shedding have been partially clarified, the mechanism that triggers CD44’s shedding at the membrane is not understood." (PMID 26347743, 2015). "We carried out real-time PCR to evaluate the effects of rs13347C/T on CD44 expression using 37 tumor tissues from untreated CRC patients with different genotypes." (PMID 26010608, 2015). "Almost all of the tumor specimens presented various degrees of CD44 expression on the cell membrane." (PMID 25823654, 2015). "CD44 knockdown in CSCs resulted in inactivation of GSK3β, induction of epithelial phenotype, and a significant decrease in the number of tumor spheres." (PMID 26322272, 2015). "The results of the current study suggest that CD44 would be an ideal target for therapy, as it would target multiple aspects of tumor biology." (PMID 26189059, 2015). "Endothelial cells have a thick, pericellular matrix rich in HA, the glycocalyx, and tumor cells can interact with this through CD44 to initiate adhesion." (PMID 26539408, 2015). "Both EMT (E‐cadherin,vimentin) and CS (CD133, CD44, aldehyde dehydrogenase) markers were analyzed through immunostaining of tumor specimens." (PMID 26471868, 2015). "The relapsing tumor has a larger proportion of CD44+ cells, than of CD133+ or EpCAM+ cells, making CD44 the most suitable therapeutic target." (PMID 25797268, 2015). "Within the tumor cell membrane, HA receptors, primarily CD44 and RHAMM, anchor the HA-high extracellular network." (PMID 26380222, 2015). "CD44 is considered as a surface biomarker of tumor stem cells for CD44+ cells with self-differentiation and proliferation, renewal and antiapoptotic potential." (PMID 25658794, 2015). "Those cells later migrate to the inside of the tumor bulk and become highly proliferative CD44+90− cells." (PMID 26000019, 2015). "Studies have shown that targeting CD44 or related signaling pathways, using RNAi strategies or with anti-CD44 antibodies, will suppress tumor growth and relapse, and increase sensitivity of these cells to chemotherapeutics." (PMID 25870596, 2015).
tumor (continued). "CD44 is able to alter tumor environments through its involvement in cell trafficking, lymph node homing, and the coordination of cytokines and growth factor signaling." (PMID 25909162, 2015). "CD44 interactions with hyaluronan (HA) play a key role in various malignancies, supporting tumor cell migration, adhesion, and survival." (PMID 25941526, 2015). "It is therefore plausible that tumor cells that want to obtain endothelial cell-like characteristics induce the expression of CD44 to enable them to form vasculogenic structures." (PMID 26189059, 2015). "HA fragments are pro-inflammatory and activate signaling pathways that promote survival, migration, and invasion within both tumor and host cells through binding to HA receptors such as CD44 and RHAMM/HMMR." (PMID 26106384, 2015). "Firstly, CD44 inhibition would target the most aggressive, most dedifferentiated, vasculogenic tumor cells." (PMID 26189059, 2015). "Western blot analysis of these tumor cells showed that cardamonin inhibited the expression of Oct4, c-Myc, and CD44 induced by poly(I:C) stimulation." (PMID 25257174, 2015). "Ligands for CD44 are hyaluronic acid and osteopontin, which can promote tumour cell growth and chemotaxis, respectively." (PMID 28536399, 2015). "This supports our data demonstrating the expression of CD44 on vasculogenic tumor cells, as these cells have aborted their original cell-specific lineage." (PMID 26189059, 2015). "Conversely, the steps in tumor progression regulated by alternative splicing of CD44 still need to be defined." (PMID 25904917, 2015). "After differentiation, the susceptibility of tumor cells to NK cell-mediated lysis, the surface expression of CD54, MHC-1, B7H1, and CD44, and the induction of IFN-γ and IL-8 secretion by NK cells were assessed." (PMID 26697005, 2015). "IHC analysis of tumor sections revealed that the AR-42-treated mice displayed significant lower CD44 staining compared with the control group." (PMID 26429859, 2015). "In this paper, using PDACs from patients, preserved as xenografts in nude mice, we report that cells expressing the CD44 marker are at the source of the residual tumor, following standard antitumoral treatment." (PMID 25797268, 2015). "Tumor derived from CD44− C3A-iCSCs also displayed well-differentiated tumor cells compared to CD44+ C3A-iCSCs, which suggested CD44− C3A-iCSCs derived tumor cells exhibited lower malignant degree." (PMID 26540347, 2015). "We have previously demonstrated that pharmacologic inhibition of c-Met in MHCC97-H cells results in a reduction of tumor growth and decreased CD44 expression." (PMID 25886575, 2015). "Both integrin and CD44 receptors are involved in cell adhesion, in which they lead to transduction of overlapping signaling pathways that mutually interact as an OPN-integrin-CD44 axis in tumor progression." (PMID 26068949, 2015). "Consistent with our data, in other tumor cell-lines derived from breast and of other tissues the CD24+/CD44+ cell subpopulation has previously been associated with a CSC-enriched phenotype due to increased tumorigenicity in mice." (PMID 26020648, 2015). "They assessed the levels of miR-34a expression as a percentage of expression from CD44+ cells vs CD44− in each model by quantitative RT-PCR, as compared to levels of let-7b, a known tumor suppressive miRNA that is underexpressed in CD44+ cells." (PMID 26231042, 2015). "Cluster of differentiation 44 (CD44) signaling interactions play a key role in various malignancies, supporting tumor cell migration, adhesion, and survival." (PMID 26608463, 2015). "Irregular or prolonged CD44 and CD44–HA interaction, however, can lead to fibrosis, scarring, immunopathology, and tumor growth." (PMID 25954275, 2015).
tumor (continued). "oHAs were attached to PE and incorporated into the liposomes, which increased their recognition, cytotoxicity, and transfection efficiency by tumor cells expressing high levels of CD44 in a temperature-dependent manner." (PMID 25999946, 2015). "This is the first study to examine the potential for CD44 targeted HA-PEI/HA-PEG-based nanoparticle to deliver MDR1 siRNA to tumor cells in vivo to overcome drug resistance." (PMID 25687880, 2015). "Recently, it was shown that LRP1 binds to CD44 and thus regulates the adhesive properties of tumor cells." (PMID 26103567, 2015). "In this study, overexpression of CD44 was found in the tumor recurrence of xenograft mouse model undergoing paclitaxel treatment." (PMID 25823654, 2015). "In recent in vivo reports, there was effective tumor shrinkage in xenograft models by suppressing CD44 mRNA and protein." (PMID 25823654, 2015). "The cell surface marker profiles of CD44+or ALDH+ have been shown previously to enrich for stem/progenitor-like cells with increased capacity for tumour initiation." (PMID 26667821, 2015). "Early observations have demonstrated a significant correlation between CD44 and tumor mortality, and growing evidence has suggested that CD44 is not only a CSC marker but also a mediator of many functional roles of CSCs." (PMID 26322272, 2015). "Interactions between HA and CD44 have been shown to play essential roles in tumor cell growth, survival, migration, and metastasis." (PMID 26322272, 2015). "MMP7 produced by tumor cells cleaved to the extracellular domain of CD44, which is a participant in the creation of an anti-adhesive milieu for tumor migration." (PMID 25885552, 2015). "c-Met and CD44 have been utilized as cell surface markers to identify mesenchymal tumor-initiating stem-like cells (TISC) in several cancers including HCC." (PMID 25886575, 2015). "This suggests that tumor cells enhance their own CD44 cleavage via Hyal activity and oligo-HA generation to promote their own motility, tumor invasion, and metastasis." (PMID 26029216, 2015). "After knocking out CD44, liver CSCs exhibited lower tumor characters and higher stemness level, CD44− liver CSCs then acquire phenotype similar to normal liver progenitor cells." (PMID 26540347, 2015). "A noteworthy feature of the tumour line was its richness in CSCs (>60% CSCs based on flow cytometric analyses of particular markers (for example, CD44+ cells)." (PMID 26437858, 2015). "The observation that tumor cells adopt mechanisms of angiogenic endothelial cells to increase their chances to survive is important and suggests that targeting of CD44 is a promising anti-cancer approach." (PMID 26189059, 2015). "CD44 is a widely known cancer stem cells marker in various cancers and validated to function in tumor growth, survival and tumor metastasis." (PMID 26540347, 2015). "In this work, using PDACs from patients, preserved as xenografts in nude mice, we demonstrated that a residual PDAC tumor originated from a small number of CD44+ cells present in the tumor." (PMID 25797268, 2015). "A6 binds to CD44 resulting in the inhibition of migration, invasion, and metastasis of tumor cells, and the modulation of CD44-mediated cell signaling." (PMID 25870596, 2015). "This injection caused an intense fluorescent appearance of the Qdot800 at the tumor site, mostly likely due to specific binding of HA to activated CD44 in the xenografts." (PMID 25909172, 2015). "CD44 is an extensively expressed class I transmembrane glycoprotein distributed on many normal cells and tumor cells." (PMID 26408312, 2015). "Our in vivo study showed that the average tumor volume in mice administrated with the combination of HA-PEI/HA-PEG/MDR1 siRNA CD44 targeted nanoparticle and paclitaxel was significantly smaller than that observed in control groups." (PMID 25687880, 2015). "Secreted FK506-binding protein like (FKBPL) and its peptide derivatives inhibit cell migration and tumor angiogenesis by targeting CD44." (PMID 25767277, 2015).
tumor (continued). "The CD44 shedding induced by cholesterol depletion is also seen in other tumor cells, such as pancreatic cancer cells." (PMID 26347743, 2015). "In particular, the CD44+/CD24low/− combination represents the molecular phenotype of breast CSC sub-population which represents the part of the tumor that can survive during colonization and promote cancer cell invasion." (PMID 25629807, 2015). "We demonstrate that, in the context of GBM tumor tissue, expression of coexpression modules associated with CD133, CD44 and CD15 mRNA are markers of GBM molecular subtype independent of cancer stem cell molecular signatures." (PMID 25749043, 2015). "After primary systemic therapy, the proportions of CD44+/CD24− tumor cells were significantly increased." (PMID 25429827, 2015). "Thirdly, the advantage of a CD44-based anti-cancer strategy would be the targeting of the tumor stem cell compartment." (PMID 26189059, 2015). "In summary, low expression of KAI1/CD82 combined high expression of CD44, MMP7 and β-catenin was found to be associated with tumor metastasis and poor prognosis in CRC." (PMID 26408312, 2015). "In the present report, we showed that CD44 expression is increased in aggressive, vasculogenic network forming tumor cells." (PMID 26189059, 2015). "More recently, nanoparticles and liposomes containing an anti-CD44 antibody, as well as, imaging reagents (e.g., cDNAs for monomeric red fluorescence protein or luciferase) have been used to target tumor detection and imaging." (PMID 25954275, 2015). "CD44 knock-down increased survival and decreased overall tumor burden at multiple sites, including the skeleton in vivo." (PMID 25888636, 2015). "HA oligosaccharides were attached to PE and incorporated into the liposomes, which increased their recognition, cytotoxicity, and transfection efficiency by tumor cells expressing high levels of CD44 in a temperature-dependent manner." (PMID 26448753, 2015). "CD44 has a well-documented tumor-promoting activity that includes promoting tumor cell growth, differentiation and metastasis." (PMID 26010608, 2015). "Most scholars believe that the CD44 gene can be used as a new tumor marker, which greatly facilitates the early diagnosis of malignant tumor recurrence and metastasis." (PMID 26666511, 2015). "To investigate the potential relationship between single marker-positive versus double marker-positive PCa cells with respect to their tumor-regenerating activity, we compared CD44+α2β1+ versus CD44+ and α2β1+ cells in Du145 and LAPC9 models." (PMID 26246472, 2015). "Although CD44 knockdown tumor cells kept their ability to form vascular structures, the capacity to do so was significantly reduced." (PMID 26189059, 2015). "Immunohistochemical staining had shown that the tumour was strongly positively stained for smooth muscle actin, calponin, and CD44 and focally positive for desmin." (PMID 26640482, 2015). "We also found that the growth inhibitory effect of ICG-001 is correlated with the downregulated expression of the NPC CSC-like markers SOX2 and CD44, and the upregulated expression of the tumor suppressive microRNA-145 (miR-145)." (PMID 25897700, 2015). "Based on the proportion of positive tumor cells and the intensity of the staining, 62% of cases were considered strongly positive for CD44." (PMID 25888636, 2015). "CD44 expression also correlated with Furhman grade (RR = 0.61, 95% CI 0.48–0.77), tumour recurrence (RR = 7.42, 95% CI 3.74–14.70) and MVI (Microvascular invasion) (RR = 3.63, 95% CI 1.97–6.71)." (PMID 26287771, 2015). "The low percentage of CD24-high tumours in the TNBC subtype also agrees with the enrichment of CD44+/CD24−/low cells in triple-negative invasive breast cancer." (PMID 26444008, 2015). "MDA-MB-231 cells are CD44+ and we observed that the majority of xenograft tumor cells were CD44+ MDA-MB-231 cells with very few mouse cells." (PMID 26334999, 2015).
tumor (continued). "For example, tumor-derived cells express CD44 in a high-affinity state that is capable of binding and internalizing HA." (PMID 26448753, 2015). "Interaction of HA with CD44 is often associated with increased cell motility and invasion, although numerous reports have demonstrated that CD44 can also modify growth and therapeutic resistance of tumor cells." (PMID 26106384, 2015). "Kaplan-Meier analysis confirmed that high CD44 expression predicted for reduced disease-free survival in lymph node-positive patients (p = 0.019) and patients with large tumor size (> 2.5 cm) (p = 0.012)." (PMID 25888636, 2015). "From the six signature proteins (HLA-A, CFH, CD44, PTPRJ, HP, and CDH5), only CD44 has been previously associated with CRC prognosis in tumor specimens from 74 patients that were assayed by immunohistochemistry." (PMID 26253080, 2015). "CD44 is a broadly distributed cell surface glycoprotein found on hematopoietic cells, fibroblasts, and numerous tumor cells." (PMID 25999946, 2015). "This phenomenon has been observed in other tumor models and appears to be a response that is dependent on oligo-HA and CD44 interaction." (PMID 26029216, 2015). "In the context of modulating macrophage responses to tumor cells, functional studies demonstrate a link between CD44:HA binding and generation of immunosuppressive macrophages." (PMID 26106384, 2015). "CD44 plays a key role in the continuity of many tumor cells by transmitting survival and anti-apoptotic signals." (PMID 26322272, 2015). "Overall, our data implies that CD44 can promote tumor cell adhesion to endothelial barriers and facilitating localized invasion/colonization within the tissue, rather than promoting or increasing the rate of cell proliferation at secondary sites." (PMID 25888636, 2015). "In this study, we investigated CD44 expression in NPC cells and determined that CD44-positive cells also expressed OCT4 in human tumor tissue samples." (PMID 26202311, 2015). "The CD44 deficient murine CLL cells had marked signs of apoptosis, e.g., increased expression of cleaved caspase-3, suggesting a role of CD44 in tumor cell survival in the spleen microenvironment." (PMID 25941526, 2015). "CD44, a receptor of hyaluronic acid and a marker of tumor stem cells, is a kind of cell adhesion factors." (PMID 25929323, 2015). "We demonstrated that administration of HA-PEI/HA-PEG/MDR1 siRNA CD44 targeted nanoparticle followed by paclitaxel treatment had similar effects on tumor growth as the control group of tumor treated with saline and paclitaxel in SKOV-3 xenograft model." (PMID 25687880, 2015). "In conclusion, our results identified CD44 as a novel marker of vasculogenic tumor cells and show an important function for CD44 in the formation of vascular-like tumor cell networks." (PMID 26189059, 2015). "We showed that the average tumor volume in mice administrated with the combination of HA-PEI/HA-PEG/MDR1 siRNA CD44 targeted nanoparticle and paclitaxel was significantly smaller than that observed in control groups." (PMID 25687880, 2015). "In fact, we even observed tumor development with a single CD44+α2β1+ LAPC9 cell (see discussion below)." (PMID 26246472, 2015). "Silencing CD44 abrogates cancer stem cell properties of tumor initiating cells from decreased the number and size of tumorspheres and the number of colonies to tumourigenic potential." (PMID 25605020, 2015). "The overexpression of CD44ICD in CD44-depleted MDA-MB-231 cells also promoted tumor growth in xenografted mice as well as in control cells." (PMID 25909162, 2015). "CD44 was originally described as a mediator of lymphocyte homing to peripheral lymphoid tissues and is closely correlated with tumor cell proliferation, metastasis and patient outcome." (PMID 28031890, 2015).